CD40 (CD40 molecule)
Diseases named in the same sentence as CD40 in open-access papers (continued):
Sharing a sentence is not in itself a finding about the gene and the disease.
breast carcinoma (60 papers, 2005 to 2026). "In 3951 patients with breast cancer, survival analyses showed that high CD40 mRNA expression was highly associated with improved overall survival (OS) (hazard ratios of 0.62–0.77, P =3.4e-11)." (PMID 32256143, 2020). "We detected CD40 gene expression along with its 3 different splice variants (variants 1–3), predominantly in the triple-negative subgroup of breast cancer cell lines." (PMID 32256143, 2020). "The results of the overall survival analysis showed that high CD40 gene expression, particularly in the triple-negative subgroup of breast cancer patients, is associated with better survival." (PMID 32256143, 2020). "In this study, we showed the transcriptional variants of the CD40 gene in different breast cancer cell lines." (PMID 32256143, 2020). "In conclusion, investigation of CD40 splice variants’ expression among different types of breast cancer cells is important for targeting the secreted or full-length form of CD40 mRNA." (PMID 32256143, 2020). "Our findings primarily show that CD40 gene polymorphisms contribute to sporadic breast cancer risk and have a significant association with clinicopathological features among Chinese Han women from the Heilongjiang Province." (PMID 21912605, 2011). "CD40 gene polymorphisms appear to contribute to sporadic breast cancer risk and had a significant association with clinicopathological features among Chinese Han women from northeast China." (PMID 21912605, 2011). "And our results indicate that some of the alleles, genotypes and haplotypes of the CD40 gene are associated with the risk and the clinicopathological features of breast cancer." (PMID 21912605, 2011). "Our preliminary data showed a statistically significant association between the four CD40 gene SNPs and sporadic breast cancer risk (additive P = 0.0223, 0.0012, 0.0013 and 0.0279, respectively)." (PMID 21912605, 2011). "Wingett and colleagues observed that, in contrast to normal B cells, in which CD40 signaling provides a potent survival signal, CD40 ligation in breast carcinoma cells results in growth inhibition and enhanced susceptibility to Fas-mediated apoptosis." (PMID 18086299, 2007). "Similarly, MCF-12A normal breast cells showed a similar transcriptional pattern as these breast cancer cells for CD40 splice variants." (PMID 32256143, 2020). "Six out of 8 breast cancer cell lines expressed CD40 variant/variants." (PMID 32256143, 2020). "In addition to the transcriptional levels of CD40 splice variants, investigation of protein levels of these variants will allow the categorization of breast cancer cells and reveal their potential as an immunotherapeutic target." (PMID 32256143, 2020). "Based on these data, we speculated that SNPs in CD40 independently or synergistically influence the susceptibility to sporadic breast cancer." (PMID 21912605, 2011). "We investigated the association between CD40 gene polymorphisms and the sporadic breast cancer." (PMID 21912605, 2011). "Due to the complex functions of the CD40 pathway in the prognosis of cancer, polymorphisms of the CD40 gene that have crucial roles in the translational efficiency of the CD40 protein may affect the risk and prognosis of breast cancer in Chinese Han women." (PMID 21912605, 2011). "In summary, we demonstrate for the first time complete reversal of ICB resistance in ER + breast cancer through CD40 agonism." (PMID 40585246, 2025). "This can explain the seemingly low expression levels of HLADR and CD40 on primary breast cancer CD169+ TAMs in the proteome analysis since B cells express high levels of HLADR and CD40 in general." (PMID 37404831, 2023). "We tested the possibility that the combination of panobinostat/venetoclax (PV) with anti-CD40 immunotherapy would provide maximal therapeutic efficacy in breast cancer." (PMID 35788566, 2022). "CD40 was primarily expressed in DCs in the pancreatic model and macrophages in the breast cancer model." (PMID 36451859, 2022).
breast carcinoma (continued). "We found the triple combination of panobinostat, venetoclax and anti-CD40 to be curative and well-tolerated across multiple models of mammary cancer." (PMID 35788566, 2022). "that NDV infected MCF-7 cells have beneficial effects on the antigen presentation capacity of breast cancer patient derived dendritic cells demonstrated by an upregulation of CD40, CD80, CD83, CD86 and MHC class II (HLA-DR)." (PMID 34777344, 2021). "CD40LG inhibited the in vitro growth of CD40+ human breast cancer lines by blocking the cell cycle and inducing apoptosis of breast cancer cells." (PMID 33907159, 2021). "CD40L was expressed on a CD40-positive breast cancer cell line (T47D) and induced an antiapoptotic signal when cells were exposed to cytotoxic agents." (PMID 33907159, 2021). "For example, Ixabepilone, which was associated with CD40, CXCR4, IL6, and SERPINE1, were used in locally advanced breast cancer and metastatic breast cancer, can potentially be repurposed to treat OCSCs." (PMID 32977853, 2020). "Ligation of the trimeric recombinant protein (rCD40LG) with CD40 leads to growth inhibition of breast cancer cells." (PMID 32256143, 2020). "Here, we analyzed both CD40/CD40 ligand expression in breast cancer cells and tissues using public data sets and overall survival analysis in ungrouped breast cancer patients, as well as in the triple-negative breast cancer subtype." (PMID 32256143, 2020). "CD40 has been detected in all compartments, namely membrane, cytoplasm, and nucleus, in breast cancer (u1d45; u1d46)." (PMID 32256143, 2020). "RNA-seq analysis of 66 human breast cancer cell lines derived from the CCLE data setshowed that breast cancer cells display low CD40 expression." (PMID 32256143, 2020). "Prognostic value of CD40 gene expression was determined in breast cancer using the Kaplan–Meier plotter." (PMID 32256143, 2020). "In accordance, the expression levels of CD40/CD40L have also been found to be increased in breast cancer, displaying a positive relationship with pathological grade." (PMID 28650989, 2017). "CD40 stimulation by its soluble recombinant human CD40 ligand directly inhibits human breast cancer cells in vitro and in SCID mice model." (PMID 28085094, 2017). "After 8 cycles of NAC, women whose breast cancers showed a PPR also had significantly lower levels of expression of mDC1 CD40 (p = 0.001) and CD86 (p = 0.001), compared with HFDs." (PMID 28913366, 2017). "In conclusion, our data showed that the mRNA expression levels of PD-L1, FOXP3, CD80, CD40, and CD14 in PBMCs were associated with breast cancer burden." (PMID 26942414, 2017). "In fact, we show here that up-regulation of the mRNA expression levels of PD-L1, FOXP3, CD80, CD40, and CD14 in PBMCs is associated with breast cancer." (PMID 26942414, 2017). "Taking advantage of CD40 overexpression in the majority of human breast cancers, the efficacy of an OAd expressing CD40L (AdEHCD40L) has been demonstrated." (PMID 28536390, 2016). "In summary, an interaction between CD40 on MDA-MB231 breast cancer cells and CD40L on activated T cells increases the production of Th17 differentiating cytokines including TGF-β, IL-1β, IL-6, and IL-21." (PMID 25992978, 2015). "Based on our findings regarding CD40 and CD40L expression, the function of CD40 signaling in breast cancer cells was investigated with CD40 stimulating antibody, soluble CD40L and activated T cells." (PMID 25992978, 2015). "First, the expression of CD40 was examined in the human breast cancer cell lines MDA-MB231 and Hs578T." (PMID 25992978, 2015). "CD40 was highly expressed in the breast cancer cell line MDA-MB231, and its stimulation with CD40 antibodies caused the up-regulation of TGF-β." (PMID 25992978, 2015). "This study investigated the role of CD40 in breast cancer cells and its role in immunosuppressive function and tumor progression." (PMID 25992978, 2015).
breast carcinoma (continued). "We found that CD40 is highly expressed in the breast cancer cell line MDA-MB231 and hardly expressed in the breast cancer cell line Hs578T." (PMID 25992978, 2015). "CD40 expression has also been shown to play a role in the activation of dendritic cells, which are promising candidates for breast cancer immunotherapy." (PMID 18086299, 2007). "Several preclinical studies from different laboratories have suggested that the CD40 signaling pathway plays a role in the modulation of chemosensitivity in breast cancer cells." (PMID 18086299, 2007). "CD40 was found detectable in 2 of the 3 breast carcinoma cell lines (BCC), in all 6 renal cell carcinoma lines (RCC), in the HTB81 prostatic carcinoma and the HCT116 colon carcinoma cell lines as well as in 5 of 5 NHL cell lines tested (not shown)." (PMID 16545138, 2006). "In contrast, in CD40 expressing breast carcinoma cell lines, the protective effect of CD40L was found to be caspase-independent." (PMID 16545138, 2006). "However, in contrast to breast cancer where CD40 agonists enhance TLS 49, GIST TLS are spontaneously amplified by imatinib." (PMID 41510151, 2026). "Our findings suggest agonistic CD40 therapy may be a viable strategy for immune activation and long-lasting immunity in ER + breast cancer." (PMID 40585246, 2025). "Although antigen-specific T cell responses remain to be critically evaluated, overall, these results suggest the triple combination of lower-dose panobinostat, venetoclax and anti-CD40 as a highly synergistic therapeutic strategy for long-term breast cancer control." (PMID 35788566, 2022). "A clinical study of CDX-1140, a CD40 agonist, for use as a monotherapy or in combination with the anti-PD-1 mAB, pembrolizumab, has been initiated in patients with advanced malignancies, including breast cancer (ClinicalTrials.gov Identifier: NCT03329950)." (PMID 33747948, 2021). "After transfer, these Tregs lose their FoxP3 expression and migrate into B-cell follicles, in which they differentiate into TFH cells on CD40/CD40L-dependent interaction with B cells and consistent with the detection of TFH in breast cancer- and NSCLC-associated TLS." (PMID 33763071, 2021). "Furthermore, results from a recent orthotopic breast cancer study suggest that combination treatment using anti-PD-1 and a CD40 agonist promote tumor immunogenicity." (PMID 33747948, 2021). "Other studies have suggested that CD40 may induce apoptosis in breast carcinoma cells by upregulating Fas expression induced by CD40 ligation." (PMID 33747948, 2021). "Moreover, it has been shown that cytoplasmic expression of CD40 is correlated with a better prognosis in breast cancer." (PMID 32256143, 2020). "For this reason, we next examined whether CD40 also has a role in the immune escape mechanism of breast cancer through the production of TGF-β." (PMID 25992978, 2015). "Therefore the methylation of CD40 supported the evidence for prediction of breast cancer and made an important contribution to the treatment of breast cancer." (PMID 25774687, 2015). "CD40 haplotype frequencies in breast cancer patients and controls." (PMID 21912605, 2011). "Genotyping of CD40 gene SNPs in breast cancer patients and controls." (PMID 21912605, 2011). "Our GSEA results suggest that a CD40 gene signature may be able to identify a subset of patients with HER-2-overexpressing breast cancer who are more likely to achieve pCR in response to trastuzumab-plus-T/FEC therapy." (PMID 18086299, 2007). "CD40 signaling may play a role in determining response to trastuzumab-plus-T/FEC therapy in patients with HER-2-overexpressing breast cancer." (PMID 18086299, 2007). "Our study reveals that the levels of sPD-L1 or IL-10 in the serum or PD-1+ Bregs in the PBMCs of breast cancer patients might be predictors for immunotherapy, and combination PD-L1 antagonist and CD40 agonist Abs might be a more efficient immunotherapy for TNBC." (PMID 35935985, 2022).
breast carcinoma (continued). "Our test of this hypothesis by systemic treatment of the E0771 orthotopic breast cancer model with a combination of venetoclax and an anti-CD40 agonist showed that this combination reduced tumor growth rate and increased overall survival with 60% of mice surviving for >12 months." (PMID 35788566, 2022). "In both the METABRIC and TCGA datasets, downregulation of genes such as CD4 and CD40 may indicate decreased CD4+ T cell response or decreased CD40-mediated apoptosis, both of which are correlated with tumor regression, better response to therapy, and higher overall breast cancer survival." (PMID 29796176, 2018). "A clinical study reported a significant difference in expression of cytoplasmic CD40 between breast cancer subtypes, and cytoplasmic expression of CD40 is related to a better prognosis, which suggest that CD40 may have potential as a new prognostic factor in breast cancer." (PMID 28085094, 2017). "In addition to B cells, CD40 is also expressed in several kinds of tumor cells, such as breast cancer, ovarian cancer, colon cancer, and melanoma; however, its specific roles are still largely unknown." (PMID 25992978, 2015). "In Monocyte group, CD40 on CD14-CD16+ monocyte (P = 0.016, OR = 1.024, 95%CI = 1.004~1.045) and were positively correlated with breast cancer." (PMID 39418291, 2024). "In a humanized mouse model for CD40 and FcγRs, 2141-V11 induced TLS formation in mice bearing orthotopic breast carcinoma, correlating with local and abscopal antitumor effects, systemic immune activation, and immune memory." (PMID 38883779, 2024). "Regarding CD40 and CD40L expression and cancer prognosis, a similar analysis was made, but related to breast cancer, which showed that high expression of CD40 and CD40L is also associated with better prognosis in this type of cancer." (PMID 37970926, 2023). "To address this need, here we developed an in vitro heterotypic human macrophage-ER+ PR+ HER2+ breast cancer cell 3D model, referred to as macrophage-tumor spheroid (MTS), and used it to investigate the effect of dual CSF1/CSF1R inhibition and CD40 activation." (PMID 37346794, 2023). "Further analysis of the genetic structure and functionality of CD40 and CD40LG would allow the development of more useful prognostic factors and prognostic prediction tools in breast cancer subtypes." (PMID 32256143, 2020). "This study showed that LPS-stimulated human dendritic cells (DCs) decreased the expression of HLA-DR, CD83 and costimulatory molecules (CD40, CD80 and CD86) following coculturing with CTLA-4+ breast cancer cells." (PMID 28099147, 2017). "Various cancer-related cell-surface proteins are known to be transported into the nucleus in several cancers, including ErbB2 (breast cancer), CD40 (lymphoma), and CD44 (breast cancer)." (PMID 23638030, 2013). "Our previous work in breast cancer patients has clearly demonstrated that such DCTs and DCTIs have an optimal antigen uptake capacity and upregulation of CD86, CD40 and class I, but low levels of CD83, as is expected of non-terminally mature DCs." (PMID 19298672, 2009). "Tong and colleagues, in their study using CD40-positive (T47D and BT-20) and CD40-negative (MCF-7 and ZR-75-1) cell lines, likewise examined the growth outcome of CD40 ligation in human breast cancer cells." (PMID 18086299, 2007). "Therapeutic strategies targeting TAMs in breast cancer have evolved from depletion approaches (CSF1/CSF1R blockade) to inhibition of monocyte recruitment (CCL2/CCR2 axis), functional reprogramming (CD40 agonism, PI3Kγ inhibition), and macrophage-directed checkpoint modulation (CD47-SIRPα axis)." (PMID 42122206, 2026). "Agonistic CD40 therapy has the potential to bridge the gap between innate and adaptive immunity by enabling robust CD8 + T cell priming and activation, potentially overcoming the immunosuppressive barriers characteristic of ER + breast cancers." (PMID 40585246, 2025).
breast carcinoma (continued). "Specificity of the vector was demonstrated by enhanced cytotoxicity in CD40 positive breast cancer cells and decreased CD40L expression in nonmalignant epithelial cells." (PMID 28536390, 2016). "These were Estrogen Biosynthesis (HSD17B7 and HSD17B12), Estrogen-Dependent Breast Cancer Signaling (HSD17B7 and HSD17B12), Hepatic Fibrosis/Hepatic Stellate Activation (CD14 and CD40), Tight Junction Signaling (CDSF1 and OCLN), and Dopamine-DARPP32 Feedback in cAMP Signaling (CACNAID and CSNK1E)." (PMID 23759029, 2013). "CD40-induced NF-κB, which also involves TNIK, protects cells from apoptosis in some low-grade B-cell malignancies and promotes cell transformation of epithelial cells, for instance in breast cancer." (PMID 22904686, 2012). "As demonstrated by the quantitative expression levels (QIF scores), some degree of CD40 expression in the tumor compartment was found in all the tested tumor types (bladder, colon, gastric, head and neck, NSCLC, ovarian, pancreatic and renal), with the exception of breast cancer." (PMID 36894898, 2023). "Interestingly, this multi-tumor survey returned a negative result for CD40 expression in breast cancer." (PMID 36894898, 2023). "Other studies have examined the CD40/Fas costimulatory effects on apoptosis in malignant cells and found that this also occurs in a range of tumour cell lines including the human myeloma cell line XG2, B cell lymphoma cells, breast carcinoma cell lines and chronic lymphocytic leukemia cells." (PMID 21103345, 2010). "In breast carcinoma, CD40L is expressed on non-cancer cells from a tumor environment and protects CD40+ cancer cells through a caspase-independent pathway against apoptosis caused by cytotoxic agents (e.g., CDDP and PTX) and as a result, induces a multidrug resistance." (PMID 33287223, 2020).